RPGRIP1 (RPGR interacting protein 1)
Description:
May function as scaffolding protein. Required for normal location of RPGR at the connecting cilium of photoreceptor cells. Required for normal disk morphogenesis and disk organization in the outer segment of photoreceptor cells and for survival of photoreceptor cells.
Synonyms: RGI1; LCA6; CORD13; RGRIP; RPGRIP; RPGRIP1d
Tractability: PROTAC: ubiquitination databases record sites on it.
Gene: Protein-coding gene on chromosome 14 (21,280,083 to 21,351,301, forward strand). Ensembl gene ENSG00000092200.
Subcellular location: Cell projection, cilium
Subcellular location (Human Protein Atlas): Microtubules; Primary cilium; Vesicles; Cytokinetic bridge; Cytosol; Primary cilium tip
Gene Ontology:
Molecular function: protein binding
Biological process: non-motile cilium assembly; retinal rod cell development
Cellular component: ciliary tip; cilium; photoreceptor connecting cilium; axoneme; non-motile cilium; photoreceptor distal connecting cilium
Genetic constraint (gnomAD): Loss-of-function variants: 79 observed, 103.75 expected, observed/expected ratio (o/e) 0.76, 90% interval 0.63 to 0.92. The upper end of that interval is the gene's LOEUF score, 0.92, which puts it in group 3 of 6, group 1 being the genes least tolerant of losing a copy. Missense variants: 1,104 observed, 1,210.9 expected, observed/expected ratio (o/e) 0.91, 90% interval 0.87 to 0.96. Synonymous variants: 431 observed, 453.23 expected, observed/expected ratio (o/e) 0.95, 90% interval 0.88 to 1.03.
Homologues: Orthologues: chimpanzee RPGRIP1 (98% identical), macaque RPGRIP1 (91% identical), rabbit RPGRIP1 (73% identical), dog RPGRIP1 (67% identical), mouse Rpgrip1 (65% identical), rat Rpgrip1 (65% identical), guinea pig RPGRIP1 (59% identical), pig RPGRIP1 (57% identical), tropical clawed frog rpgrip1 (34% identical), zebrafish rpgrip1 (29% identical), Caenorhabditis elegans mks-5 (16% identical), Caenorhabditis elegans C09G5.13 (4% identical). Paralogues in human: RPGRIP1L (33% identical).
Diseases named in the same sentence as RPGRIP1 in open-access papers:
RPGRIP1 is named in the same sentence as 62 diseases in open-access papers, as found by Europe PMC text mining. Sharing a sentence is not in itself a finding about the gene and the disease. The quoted sentences say what the papers report.
cone-rod dystrophy (22 papers, 2008 to 2025). Inherited retinal dystrophies that belong to the group of pigmentary retinopathies. "A homozygous variant in the MAP9 gene has been reported to accelerate disease progression in a naturally-occurring canine RPGRIP1-associated cone-rod dystrophy." (PMID 38979372, 2024). "Biallelic RPGRIP1 variants have been associated with non-syndromic human IRDs, including retinitis pigmentosa (RP), cone-rod dystrophy (CRD), and Leber congenital amaurosis (LCA) type 6." (PMID 37650070, 2023). "One of the RPGR interacting partners, the RPGR interacting protein 1 (RPGRIP1) gene is also known to mutate in patients with RP, cone-rod dystrophy or Leber congenital amaurosis (LCA)." (PMID 34209942, 2021). "Two of them presented a severe cone rod dystrophy with the clinical features characteristic for RPGRIP1-associated retinal degeneration." (PMID 33670832, 2021). "RPGRIP1 has also been reported to be associated with cone-rod dystrophy 13 (CROD 13), in which the phenotype of patients seemed to have been characterized by a rapid loss of vision in the second decade of life, but further details were not provided." (PMID 34796026, 2021). "The distinct genetic feature of RP_25 consisted of the presence of a heterozygous causative variant of cone-rod dystrophy in the RPGRIP1 gene, encoding a scaffolding protein required for the normal intracellular vesicular trafficking." (PMID 33374679, 2020). "Defects in the cilia gene RPGRIP1 cause Leber congenital amaurosis and cone-rod dystrophy in humans." (PMID 28993665, 2017). "Further, a mutation in NPHP4, another gene known to interact with RPGRIP1, was shown to be causative of cone/rod dystrophy of the wire-haired Dachshund." (PMID 22550515, 2012). "This fact is true for most forms of PRA; however, for the cone-rod dystrophies observed in the longhaired and shorthaired Dachshund breeds, with the RPGRIP1 and NPHP4 mutations, respectively, severe heterogeneity has been described for both." (PMID 22550515, 2012). "ERG recordings proved to be useful in the masked study of the present investigation for objectively detecting reduced photoreceptor function in accordance with cone rod dystrophy due to the RPGRIP1 mutation." (PMID 22550515, 2012). "Hence, we characterized the pathogenic phenotypes associated with homozygous MAP9 variant, and investigated the molecular function of MAP9 in primary cilia using the RPGRIP1-associated oligogenic canine cone-rod dystrophy model as well as cultured cells." (PMID 37650070, 2023). "Mutations in RPGRIP1 also caused juvenile retinitis pigmentosa and cone-rod dystrophy in humans." (PMID 29203866, 2017). "Mutations in RPGRIP1 cause Leber congenital amaurosis (LCA6 [MIM 605446]) and cone-rod dystrophy (CORD13 [MIM 608194]), and mutations in RPGRIP1L cause Joubert syndrome (JBTS7 [MIM 611560]) and Meckel syndrome (MKS5 [MIM 611561]), two syndromic ciliopathies with associated retinal dystrophy." (PMID 21857984, 2011). "This variant appears to be acting as a modifier, and is necessary for the RPGRIP1 mutant dogs to develop the cone-rod dystrophy phenotype." (PMID 40461693, 2025). "RPGRIP1 (RPGR Interacting Protein 1) mutations in people most commonly result in LCA type 6, although a cone-rod dystrophy phenotype is also reported." (PMID 40461693, 2025). "Mutations in the RPGR-interacting protein 1 (RPGRIP1) gene cause recessive Leber congenital amaurosis (LCA), juvenile retinitis pigmentosa (RP) and cone-rod dystrophy." (PMID 29203866, 2017). "Previous reports show that RPGRIP1 mutations can cause LCA, juvenile RP and cone-rod dystrophy in humans and early-onset retinal degeneration in mice." (PMID 29203866, 2017). "Mutations in these ciliary genes are implicated in photoreceptor degeneration related ciliopathies, such as RPGRIP1 in cone dystrophy (CD)/cone-rod dystrophy (CRD), LCA5 and CEP290 in Leber congenital amaurosis (LCA), Fam161A and OFD1 in RP." (PMID 27196396, 2016).
cone-rod dystrophy (continued). "Recent molecular studies in the English Springer Spaniel (ESS) dog have shown that PRA cases are often homozygous for a mutation in the RPGRIP1 gene, the defect also causing human RP, LCA, and cone rod dystrophies." (PMID 22550515, 2012). "Mutations in the RPGRIP1 gene have been identified as causative to human RP, LCA, and cone-rod dystrophies." (PMID 22550515, 2012). "There are strong indications that the RPGRIP1 gene is involved in the cone rod dystrophy described herein, but the genotype-phenotype discordance observed shows that the genetic background most probably is more complex than previously suspected." (PMID 22550515, 2012). "In a canine cone-rod dystrophy model, a naturally occurring 44-bp exonic insertion in RPGRIP1 (RPGRIP1ins44/ins44) is the primary disease locus while an additional homozygous variant in MAP9 (microtubule associated protein 9) (MAP9aff/aff) acts as a modifier associated with early disease onset." (PMID 37650070, 2023). "For example, mutations in RPGRIP1 can cause Leber congenital amaurosis (LCA) and cone-rod dystrophy (CORD), while mutations in RPGRIP1L may cause Joubert syndrome and Meckel syndrome, etc." (PMID 31775781, 2019). "We found these 3 patients carrying mutations not in RP related genes but in gene RPGRIP1 which was previously reported to cause Leber's congenital amaurosis and Cone-rod dystrophy." (PMID 28456785, 2017). "Moreover, mutations in RPGRIP1 have been identified as causing human LCA type 6, cone-rod dystrophy (CRD), and RP." (PMID 19936303, 2009). "Until now, four LCA genes account for congenital cone-rod dystrophy (LCA type I): GUCY2D, RPGRIP1, CEP290 and RD3 [present study]." (PMID 23308101, 2013). "Three of the genes, CNGB3, CNGA3 and GNAT2, involved in cone degeneration and seven genes and loci, ABCA4, RDH5, CORD8, CORD9, RPGRIP1, GUCY2D and CRX, reported to be involved in cone-rod dystrophies were studied." (PMID 18593457, 2008). "The genes involved in cone degeneration, CNGB3, CNGA3 and GNAT2, and the genes involved in cone-rod dystrophy, ABCA4, RDH5, Cord8, Cord9, RPGRIP1, GUCY2D and CRX, were all excluded from being involved in the cone-rod dystrophy described in this family of SWHD." (PMID 18593457, 2008). "This RPGRIP1-deficient model is an attractive alternative LCA canine model in the sense that, in contrast to RPE65, it is not a rod-cone dystrophy but a cone-rod dystrophy and that the cells to target are not the RPE but the photoreceptors." (PMID 19223988, 2009).
Leber congenital amaurosis (21 papers, 2008 to 2025). Leber congenital amaurosis (LCA) is a retinal dystrophy defined by blindness and responses to electrophysiological stimulation (Ganzfeld electroretinogram (ERG)) below threshold, associated with severe visual impairment within the first year of life. "Defects in RPGRIP1 cause a form of severe congenital retinal dystrophy (Leber congenital amaurosis, LCA), juvenile RP and cone-rod dystrophy." (PMID 29796181, 2018). "Mutations in RPGRIP1 have been associated with Leber congenital amaurosis (LCA), retinitis pigmentosa (RP) and CRD in humans, as well as inherited retinal abnormalities in mice which suggests it plays an important role in visual function." (PMID 26401320, 2014). "RPGRIP1 may be a common causative gene with early-onset severe retinal dystrophy, including Leber congenital amaurosis." (PMID 39271608, 2024). "As such, mutations in RPGRIP1 can result in several ocular conditions, including retinal dystrophies as well as retinal conditions such as Leber congenital amaurosis (LCA) and cone-rod dystrophies, and progressive vision loss." (PMID 40737315, 2025). "One of those is RPGRIP1, known to associate with LCA (Leber congenital amaurosis) as well as childhood-onset cone-rod dystrophy." (PMID 33805381, 2021). "–95 Last, RP GTPase regulator-interacting protein 1 (RPGRIP1) is related to degenerative diseases such as Leber congenital amaurosis, RP, and cone–rod dystrophy." (PMID 39546296, 2024). "Mutations in the RPGRIP1 gene have been reported to be a cause of Leber congenital amaurosis (LCA)." (PMID 18593457, 2008). "To study the effectiveness of gene perturbations in HF-iCas9 stem cells, we targeted several genes linked to Leber congenital amaurosis (LCA), a rare childhood-onset retinal dystrophy caused by mutations in the AIPL1, CRB1, and RPGRIP1 genes, among others." (PMID 36553630, 2022).
retinal degeneration (21 papers, 2009 to 2025). Degeneration of the retina. "We also assessed the localization of RPGRIP1 in the primary cilia, whose variants are the primary cause of this retinal degeneration model." (PMID 37650070, 2023). "In summary, after reviewing all previously published papers, it appears that mutations in the RPGRIP1 gene can cause severe retinal degeneration, which is usually characterized by rapid deterioration in visual function during the first years of life." (PMID 34722527, 2021). "In mouse, deletion of RPGR results in a slower retinal degeneration, while loss of RPGRIP1 leads to an early onset retinal degeneration with abnormal development of outer segments." (PMID 29796181, 2018). "Retinal degeneration has also been reported in dogs carrying naturally occurring mutations in the RPGR or RPGRIP1 gene." (PMID 29796181, 2018). "An RPGRIP1 knock-out (KO) mouse model exhibited early retinal degeneration with almost complete loss of photoreceptor cells by three months of age." (PMID 29203866, 2017). "This dog had moderately advanced retinal degeneration with ophthalmoscopically visible changes and was homozygous for the RPGRIP1 mutation." (PMID 22550515, 2012). "The present study indicates that a majority of the American ESS dogs with hereditary retinal degeneration can be associated with homozygosity for the disease causing allele of the RPGRIP1 gene." (PMID 22550515, 2012). "For this purpose, we further characterized the kinetics of the retinal degeneration and the disease phenotype in the RPGRIP1 deficient miniature longhaired dachshund (MLHD)." (PMID 19223988, 2009). "While the comparisons between the littermates clearly indicate that MAP9aff/aff causes earlier and more severe RPGRIP1-associated retinal degeneration, accumulation of larger sample sizes will be needed to provide a more general conclusion based on statistical examination." (PMID 37650070, 2023). "In Mfrprd6 eyes, a significant 1.5- to 2.0-fold decrease was observed among transcripts of genes linked to retinal degeneration, including those involved in visual cycle (Rpe65, Lrat, Rgr), phototransduction (Pde6a, Guca1b, Rgs9), and photoreceptor disc morphogenesis (Rpgrip1 and Fscn2)." (PMID 25357075, 2014). "Mutations in RPGRIP1 are associated with early onset retinal degenerations in humans and dogs." (PMID 23251588, 2012). "NPHP4 interacts with retinitis GTPase regulator (RPGR) and RPGR-interacting protein 1 (RPGRIP1), potentially establishing a connection to the development of retinal degeneration in patients with an NPHP4 mutation." (PMID 40427560, 2025). "Knockout of RPGRIP1 in mouse (referred to as RPGRIP1tm1Tili) resulted in early retinal degeneration with most of photoreceptors degenerating by 3 months of age, resembling the phenotypes in LCA patients." (PMID 26124960, 2015). "Another such gene working in concert with RPGRIP1 is CEP290, and when mutated it was found to cause hereditary retinal degeneration in cats." (PMID 22550515, 2012). "There have been reports of severe retinal degeneration with reduced but measurable rod response when examined at very young ages, as in our cases, suggesting that more severely affected cones than rods are characteristic of RPGRIP1." (PMID 37761981, 2023). "Specifically in the case of RPGRIP1, a number of studies probed this issue of phenotypic variability in the canine model of Rpgrip1 retinal degeneration, in which different ages of onset and variable severity of disease are seen in dogs with the same RPGRIP1 mutation." (PMID 34722527, 2021). "Loss of RPGRIP1 protein causes defects in ciliogenesis in the human retinal pigment epithelial (RPE) cell line (RPE1) and both abnormal development of the rod outer segments and early retinal degeneration in mice and zebrafish." (PMID 34209942, 2021).
retinal degeneration (continued). "Based on the discordance between RPGRIP1 genotype and clinical phenotype, a genome-wide association study was undertaken that identified a locus ~30 kb downstream of RPGRIP1 on canine chromosome 15 that influenced the age of onset of severe retinal degeneration or clinical blindness." (PMID 28993665, 2017). "Outside of the colony there was considerable variation in the age of onset of retinal degeneration in dogs that were homozygous for the RPGRIP1 insertion (termed RPGRIP1-mutant), which has also been identified in other breeds, including the English springer spaniel (ESS) and the Beagle." (PMID 26401320, 2014). "Among the RPGRIP1−/− dogs that showed the ‘114’ PCR fragment pattern (i.e. homozygous for polyA29), extensive phenotypic variations were still observed including early-onset and late-onset retinal degenerations and clinically normal animals." (PMID 23251588, 2012). "Although the complete association of the RPGRIP1 insertion with PRA in MLHDs remains to be established, observations of cone-rod retinal degeneration in RPGRIP1−L/−L Beagles indicate its involvement in retinal degeneration." (PMID 19936303, 2009). "The other four non-RPGRIP1−/− dogs (MLD14, 15, 18, and 19) showed no clinical signs of retinal degeneration." (PMID 19936303, 2009). "To date, the clinical literature on RPGRIP1-LCA patients clearly documents early and severe visual disturbances with nystagmus, abnormal visual acuity, nondetectable ERGs, and fundus features of retinal degeneration." (PMID 19223988, 2009).
Retinal dystrophy (10 papers, 2011 to 2025). Retinal dystrophy is an abnormality of the retina associated with a hereditary process. "RPGRIP1 mutations result in retinal dystrophies with a broad range of phenotypes, ranging from LCA as a severe form to cone–rod dystrophy as a less severe form." (PMID 31666973, 2019). "Because LCA is a rare disease, the number of subjects is too small to draw conclusions; nonetheless, structural abnormalities may be a major cause in RPGRIP1-related retinal dystrophy in the Japanese population." (PMID 37761981, 2023). "Structural abnormalities may be important genetic causes of RPGRIP1-related retinal dystrophy in Japanese patients, and WGS was useful for detecting them." (PMID 37761981, 2023). "There have been reports of the detection of non-coding variants such as CNVs and deep intron variants of RPGRIP1 from cases unresolved via WES using WGS, indicating that non-coding variants may contribute significantly to RPGRIP1-related retinal dystrophy." (PMID 37761981, 2023). "Structural variants may be important genetic causes of RPGRIP1-related retinal dystrophy in Japanese patients." (PMID 37761981, 2023). "Pathogenic homozygous and compound heterozygous variants in RPGRIP1 lead to a severe form of IRD and a clinical diagnosis of LCA or early-onset severe retinal dystrophy." (PMID 41270749, 2025). "This deletion is relatively prevalent in the Japanese population (allele frequency: 0.002) and possibly in Japanese patients with RPGRIP1-related retinal dystrophy." (PMID 37761981, 2023). "The optical coherence tomography (OCT) findings of RPGRIP1-related retinal dystrophy confirmed that although EZ length and retinal thickness tended to decrease gradually, retinal structures were relatively preserved, and visual acuities were low but maintained, as in previous reports." (PMID 37761981, 2023).
ciliopathies (9 papers, 2011 to 2023). "Recessive mutations in RPGRIP1L, which is a homolog of RPGRIP1, can cause systematic ciliopathies like Joubert syndrome-7, Meckel syndrome 5, and COACH syndrome 3, which also involve intellectual disability." (PMID 34722527, 2021). "Transition zone-localised RPGRIP1 and RPGRIP1L represent additional examples of very closely related ciliopathy proteins linked to a broad tissue pathogenesis (RPGRIP1L), versus a retinal-specific disease (RPGRIP1)." (PMID 27930654, 2016). "Mutations in the RPGR gene and its interacting partners, RPGRIP1 and RPGRIP1L, cause ciliopathies, but the function of their proteins remains unclear." (PMID 29796181, 2018). "We provide compelling evidence that RPGR, RPGRIP1 and RPGRIP1L may function in ciliopathy by regulating the activity of proteasome and mediating SOCE." (PMID 29796181, 2018). "Potentially, the number of ciliopathy patients would be much higher without Rpgrip1." (PMID 29650680, 2018).
Nystagmus (7 papers, 2009 to 2025). Rhythmic, involuntary oscillations of one or both eyes related to abnormality in fixation, conjugate gaze, or vestibular mechanisms. "Five patients were molecularly diagnosed as the LCA6 associated with RPGRIP1 variation, with typical clinical characteristics including congenital night blindness, nystagmus, and visual defect, at an early age." (PMID 34796026, 2021). "Patients with RPGRIP1 mutations have degeneration of both rod and cone photoreceptor cells, and in early life they experience a severe loss of central acuity, which leads to nystagmus." (PMID 19223988, 2009). "We applied TruSight One Clinical Exome sequencing to examine a bioinformatic gene panel of 65 IRD genes, which identified RPGRIP1 variants in 2 patients, LCA-1 and LCA-2, with poor vision and nystagmus manifested in the first 3 months of life." (PMID 41270749, 2025). "Based on positive reports in the different publications, the prevalence of nystagmus among RPGRIP1 patients is at least 45% (103 out of the 228 patients)." (PMID 34722527, 2021).